FXR2 (FMR1 autosomal homolog 2)
Description:
mRNA-binding protein that acts as a regulator of mRNAs translation and/or stability, and which is required for adult hippocampal neurogenesis (By similarity). Specifically binds to AU-rich elements (AREs) in the 3'-UTR of target mRNAs (By similarity). Promotes formation of some phase-separated membraneless compartment by undergoing liquid-liquid phase separation upon binding to AREs-containing mRNAs: mRNAs storage into membraneless compartments regulates their translation and/or stability (By similarity). Acts as a regulator of adult hippocampal neurogenesis by regulating translation and/or stability of NOG mRNA, thereby preventing NOG protein expression in the dentate gyrus (By similarity).
Synonyms: FXR2P; FMR1L2
Tractability: PROTAC: ubiquitination databases record sites on it; its protein half-life has been measured; a small molecule that binds it is known.
Gene: Protein-coding gene on chromosome 17 (7,591,230 to 7,614,897, reverse strand). Ensembl gene ENSG00000129245.
Subcellular location: Cytoplasm, Cytoplasmic ribonucleoprotein granule; Cytoplasm; Postsynapse
Subcellular location (Human Protein Atlas): Cytosol
Gene Ontology:
Molecular function: identical protein binding; protein binding; protein heterodimerization activity; protein homodimerization activity; RNA binding; mRNA 3'-UTR binding; translation regulator activity; mRNA binding; nucleic acid binding
Biological process: animal organ development; dentate gyrus development; mRNA destabilization; mRNA transport; positive regulation of long-term neuronal synaptic plasticity; positive regulation of translation; regulation of mRNA metabolic process; regulation of mRNA stability; regulation of translation at presynapse, modulating synaptic transmission; regulation of translation
Cellular component: cytoplasm; cytoplasmic stress granule; cytosol; membrane; neuron projection; nucleus; postsynapse; cytoplasmic ribonucleoprotein granule; presynapse
Genetic constraint (gnomAD): Loss-of-function variants: 8 observed, 44.95 expected, observed/expected ratio (o/e) 0.18, 90% interval 0.1 to 0.32. The upper end of that interval is the gene's LOEUF score, 0.32, which puts it in group 1 of 6, group 1 being the genes least tolerant of losing a copy. Missense variants: 500 observed, 593.45 expected, observed/expected ratio (o/e) 0.84, 90% interval 0.78 to 0.91. Synonymous variants: 229 observed, 215.3 expected, observed/expected ratio (o/e) 1.06, 90% interval 0.95 to 1.19.
Homologues: Orthologues: chimpanzee FXR2 (99% identical), mouse Fxr2 (98% identical), rat Fxr2 (98% identical), pig FXR2 (98% identical), guinea pig FXR2 (96% identical), dog FXR2 (96% identical), macaque FXR2 (95% identical), rabbit FXR2 (95% identical), zebrafish fxr2 (66% identical), Drosophila melanogaster Fmr1 (36% identical). Paralogues in human: FXR1 (59% identical), FMR1 (50% identical).
Diseases named in the same sentence as FXR2 in open-access papers:
FXR2 is named in the same sentence as 32 diseases in open-access papers, as found by Europe PMC text mining. Sharing a sentence is not in itself a finding about the gene and the disease. The quoted sentences say what the papers report.
fragile X syndrome (5 papers, 2013 to 2025). A genetic syndrome caused by mutations in the FMR1 gene which is responsible for the expression of the fragile X mental retardation 1 protein. "In this way, we confirmed the interaction of FMR1, FXR1, and FXR2 of the Fragile X syndrome family as well as the E3 ubiquitin ligase MKRN2 with nsp3, both in context of single and nsp3/4 expression." (PMID 37905840, 2023). "Two genes causal for fragile x syndrome, FMR1 and FXR2, displayed a strong lysosome phenotype together with increased tau aggregation upon CRISPR loss of function." (PMID 33536571, 2021). "However, due the causal role in fragile x syndrome, most data are available about loss of FMR1 in neurons while functions of FXR1 and especially FXR2 remain largely unexplored." (PMID 41117937, 2025). "The loss-of-function mutations in the FMRP gene results in fragile X syndrome (FXS), whereas the function of FXR1 and FXR2 remains unknown." (PMID 23554595, 2013).
lung adenocarcinoma (3 papers, 2024 to 2025). A carcinoma that arises from the lung and is characterized by the presence of malignant glandular epithelial cells.
autism (2 papers, 2011 to 2015). Persistent deficits in social interaction and communication and interaction as well as a markedly restricted repertoire of activity and interest as well as repetitive patterns of behavior. "FXS is caused by mutations in the Fmr1 and/or Fxr2 gene, the autosomal homolog of Fmr1, and is characterized by mental retardation and occasionally autism and epilepsy." (PMID 22016787, 2011). "To conclude, in all three replication samples, we confirmed the association of the 8‐SNP model, derived from the broader fragile X gene family (FMR1, FXR1, FXR2, FMR2), with autism‐related behaviors, underlining the phenotypical continuum of these traits across health and disease." (PMID 26612855, 2015).
melanoma (2 papers, 2020 to 2021). A malignant, usually aggressive tumor composed of atypical, neoplastic melanocytes. "In the case of melanoma, the exact effect of FXR2 (fragile X mental retardation syndrome-related protein 2) expression regulation by miR-1290 is still poorly understood." (PMID 33918883, 2021). "The miR-1290 mimic decreased the expression of FXR2 mRNA in melanoma cells after 48h and it induced a reduction of protein level in MelJuso cells." (PMID 32183388, 2020). "In order to validate those predicted targets, we transfected four melanoma cell lines with mimics for either miR1290, miR-23a-5p or miR-23b-5p followed by expression analysis of FXR2 and IPO11 by qPCR and Western blot." (PMID 32183388, 2020).
osteosarcoma (2 papers, 2019 to 2023). A usually aggressive malignant bone-forming mesenchymal neoplasm, predominantly affecting adolescents and young adults. "However, recurrent gene fusions in pediatric cancers rarely involve these regions, with only two cases validated in 48 tumors from the MOSCATO-01 cohort (two translocations t and generating GPANK1::ABHD16A and PPP1R18::FXR2 gene fusions in eRMS and osteosarcoma cases, respectively)." (PMID 38318504, 2023).
schizophrenia (2 papers, 2015 to 2018). A major psychotic disorder characterized by abnormalities in the perception or expression of reality. "Fxr2 levels have been shown to be altered in a small group of schizophrenia patient’s brain." (PMID 30087606, 2018). "Polymorphisms in the Fxr2 and Fmr1 loci have not been associated with schizophrenia by GWAS." (PMID 30087606, 2018).
ZIKV infection (2 papers, 2018 to 2023). "We additionally tested the effect of FXR1 and FXR2 knockdown on ZIKV infection." (PMID 30511641, 2018). "For example, the increase in FXR2 subsequent to FMRP depletion could positively impact ZIKV infection." (PMID 30511641, 2018). "Specifically, we observed that the FMRP targets, FXR2, TLN1, BRD4, and PNPLA6 were elevated at the protein level as a consequence of ZIKV infection." (PMID 30511641, 2018). "Although Δ10 ZIKV infection also increased the mean level of FXR2, this effect was not statistically significant (p=0.277) compared to uninfected cells." (PMID 30511641, 2018).
Anxiety (1 paper, 2019). Intense feelings of nervousness, tension, or panic often arise in response to interpersonal stresses. "In general, both Fmr1 KO and Fmr1 KO/Fxr2 Het mice traveled more relative distance in the center compared to WT indicating lower anxiety." (PMID 30654445, 2019). "Previously published results suggested that anxiety-like behavior was the same between the Fmr1 KO and Fmr1 KO/Fxr2 KO mice based on the open field test and the light:dark box." (PMID 30654445, 2019). "However, another measure of anxiety-like behavior, the zero maze, showed a statistical trend indicating that Fmr1 KO/Fxr2 Het mice had even lower anxiety than Fmr1 KO mice." (PMID 30654445, 2019).
breast carcinoma (1 paper, 2025). "Thus, this study aimed to investigate the clinicopathological significance of FXR2, a member of the FMRP family, in primary breast cancer (BC)." (PMID 40149453, 2025).
breast tumors (1 paper, 2025). "The expression of FXR2 was found in the cytoplasm of invasive breast tumors, with no obvious membranous or nuclear staining and intensity ranging from nonexistent to high." (PMID 40149453, 2025).
COVID-19 (1 paper, 2023). A disease caused by infection with severe acute respiratory syndrome coronavirus 2. "Together with the evidence of genetic association of FXR2 to COVID-19 disease severity, our findings might suggest a role of FXR2 regarding the severity of the infection, although the physiological relevance of this RBPs remains to be experimentally assessed." (PMID 36814457, 2023). "Lastly, we linked RBPs to functional, OMICs and COVID-19 patient data from other studies, and identified MBNL1, FTO and FXR2 RBPs as potential clinical biomarkers." (PMID 36814457, 2023).
lung carcinoma (1 paper, 2024). "As a result, we investigated whether silencing PRMT5 and PRMT1 affected FXR1, FXR2 and FMRP levels in oral and lung cancer cells." (PMID 38709899, 2024).
male infertility (1 paper, 2020). The inability of the male to effect fertilization of an ovum after a specified period of unprotected intercourse. "EGFR, the signalling dysfunction of which was associated with human male infertility, might be coregulated by FXR1, FXR2, and HNRNPA1 (all of these three bind EGFR from CLIP experiments), G3BP2, G3BP1, FMR1, and SRSF7." (PMID 32316190, 2020).
memory impairment (1 paper, 2019). "Like FMRP, FXR2P is expressed in brain with a similar regional distribution and mice deficient in FXR2P (Fxr2 KO) exhibit some of the same behavioral deficits seen in Fmr1 KO mice such as hyperactivity and learning and memory impairments." (PMID 30654445, 2019). "In passive avoidance, we find that Fmr1 KO/Fxr2 Het mice have more profound learning and memory impairments than do the other genotypes studied." (PMID 30654445, 2019).
oral cancer (1 paper, 2024). "Interestingly, PRMT1-silenced cells did not change the protein levels of FXR1 or FXR2, indicating that FXR1 may be a direct substrate of PRMT5 in oral cancer cells." (PMID 38709899, 2024).
pancreatic cancer (1 paper, 2025). "According to the Human Protein Atlas, the expression of FXR2 shows limited specificity in cancer; nonetheless, FXR2 overexpression appears advantageous for the survival of patients with pancreatic cancer." (PMID 40149453, 2025). "Although FXR2 expression has little specificity in cancer, the Human Protein Atlas indicates that the overexpression of FXR2 is a good prognostic marker in pancreatic cancer." (PMID 40149453, 2025).
prostate carcinoma (1 paper, 2020). A carcinoma that arises from epithelial cells of the prostate gland. "NFKB2, which is involved in aberrant activation of androgen receptor in prostate cancer cells, might be coregulated by FXR2 and HNRNPA1 proteins based on our motif enrichment analysis." (PMID 32316190, 2020). "RASSF2, which is a tumor-suppressor in the prostate cancer mouse model, might be coregulated by FXR1, FXR2, HNRNPA1, PTBP1, G3BP1, HNRNPF, and SRSF7." (PMID 32316190, 2020).
sleep disorder (1 paper, 2017). A change from the patient's baseline sleeping pattern, in the hours slept and/or an alteration/dysfunction in the stages of sleep. "Our data highlight the importance of the fragile X genes (Fmr1 and Fxr2) in sleep physiology and confirm the utility of these mouse models in enhancing our understanding of sleep disorders in FXS." (PMID 28919851, 2017).
testis tumor (1 paper, 2020). "FGFR3, which has a role in testis tumor development might be coregulated by a different set, SFPQ, FXR2, and HNRNPA1, and all three bind it based on POSTAR2." (PMID 32316190, 2020).
type 2 diabetes (1 paper, 2024). "In our analysis pipeline, two genes, SMCO4 and FXR2, were among those identified as potential type 2 diabetes candidate genes in both EndoC-BH1 and prior primary beta cell chromatin maps." (PMID 39240351, 2024).
virus infection (1 paper, 2018). "We observed a slight increase in virus infection rate for FXR1 depletion while FXR2 knockdown significantly reduced infection." (PMID 30511641, 2018).
cancer (11 papers, 2016 to 2025). A tumor composed of atypical neoplastic, often pleomorphic cells that invade other tissues. "Members of the fragile X protein (FXP) family (FMR1, FXR1 and FXR2) are differentially expressed in most types of cancer and major neurodegenerative diseases." (PMID 41117937, 2025). "There are gaps in our understanding of the FXRP family, particularly FXR2 and its involvement in cancer, necessitating future research to promote the translation of insights from bench to bedside." (PMID 40149453, 2025). "Despite significant progress in understanding FXS, knowledge of the modulation of FXR protein family members, especially FXR2, and their regulation of key genes in cancer remains nascent." (PMID 40149453, 2025). "Among them, TNRC6, DGCR8, C17ORF85, ZC3H7B, SFRS1 and TIA1, were obviously positively associated with XIST in ≥3 cancers; while eIF4AIII, FXR1, FXR2 and C22ORF28 were significantly negatively correlated with XIST in ≥3 cancers." (PMID 36212008, 2022). "In comparison to FXR1 and FMRP, the role of FXR2 in cancer remains largely unexplored." (PMID 40149453, 2025). "Another limitation of this study is the small number of FXR2 studies in the cancer field." (PMID 40149453, 2025). "Knowledge of the clinical relevance of FXR2 in cancer, particularly BC, is primitive." (PMID 40149453, 2025).